ABHD10 (abhydrolase domain containing 10, depalmitoylase)
Description:
Acts as an acyl-protein thioesterase that hydrolyzes fatty acids from acylated residues in proteins. Regulates the mitochondrial S-depalmitoylation of the nucleophilic active site residue of peroxiredoxin-5/PRDX5, a key antioxidant protein, therefore modulating mitochondrial antioxidant ability. Also catalyzes the deglucuronidation of mycophenolic acid acyl-glucuronide, an active metabolite of the immunosuppressant drug mycophenolate.
Synonyms: FLJ11342
Tractability: PROTAC: ubiquitination databases record sites on it; its protein half-life has been measured.
Target class: Enzyme; Hydrolase
Chemical probes: ML257
Gene: Protein-coding gene on chromosome 3 (111,978,972 to 111,993,368, forward strand). Ensembl gene ENSG00000144827.
Subcellular location: Mitochondrion
Subcellular location (Human Protein Atlas): Mitochondria
Pathways (Reactome):
Metabolism: Glucuronidation
Gene Ontology:
Molecular function: hydrolase activity, hydrolyzing O-glycosyl compounds; mycophenolic acid acyl-glucuronide esterase activity; palmitoyl-(protein) hydrolase activity; protein binding
Biological process: protein depalmitoylation; xenobiotic metabolic process; glucuronate metabolic process
Cellular component: cytosol; mitochondrion; mitochondrial matrix
Genetic constraint (gnomAD): Loss-of-function variants: 20 observed, 28.02 expected, observed/expected ratio (o/e) 0.71, 90% interval 0.5 to 1.04. The upper end of that interval is the gene's LOEUF score, 1.04, which puts it in group 4 of 6, group 1 being the genes least tolerant of losing a copy. Missense variants: 335 observed, 373.6 expected, observed/expected ratio (o/e) 0.9, 90% interval 0.82 to 0.98. Synonymous variants: 138 observed, 130.9 expected, observed/expected ratio (o/e) 1.05, 90% interval 0.92 to 1.21.
Homologues: Orthologues: chimpanzee ABHD10 (100% identical), macaque ABHD10 (97% identical), rabbit ABHD10 (87% identical), dog ABHD10 (83% identical), pig ABHD10 (83% identical), guinea pig ABHD10 (77% identical), rat Abhd10 (76% identical), mouse Abhd10 (75% identical), tropical clawed frog abhd10 (58% identical), zebrafish abhd10a (57% identical), zebrafish tagln3b (55% identical).
Diseases named in the same sentence as ABHD10 in open-access papers:
ABHD10 is named in the same sentence as 11 diseases in open-access papers, as found by Europe PMC text mining. Sharing a sentence is not in itself a finding about the gene and the disease. The quoted sentences say what the papers report.
alcoholic liver diseases (1 paper, 2023). A disorder caused by damage to the liver parenchyma due to alcohol consumption. "Analyses of human samples and murine models of alcoholic liver disease (ALD) reveal that the Elk-3 target Abhd10 ameliorates hepatotoxic injury and fibrosis in ALD by downregulating PRDX5 S-palmitoylation." (PMID 37400491, 2023).
diabetes (1 paper, 2019). "There is currently no report whether ABHD10 is involved in diabetes." (PMID 31088900, 2019).
liver failure (1 paper, 2023). A liver disease characterized by the liver losing or has lost all of its function. "Next, we sought to evaluate the upstream mechanism(s) governing the dysregulation of ABHD10 and S-palmitoylated PRDX5 in the context of AH-related liver failure." (PMID 37400491, 2023).
type 2 diabetes (1 paper, 2019). "Further work can be performed to investigate the potential role of ABHD10 in type 2 diabetes." (PMID 31088900, 2019). "Through PPI and GSEA, our study found that DHRS2, ABHD10, HADH and ACLY function together in type 2 diabetes." (PMID 31088900, 2019).
tumor (2 papers, 2019 to 2025). "The expression of ABHD10 and NDUFS8 decreased only after long-term tumor treatment with si-hVDAC1." (PMID 31661894, 2019).
ABHD10 also shares sentences with these, for which no sentence is quoted: alcoholic hepatitis (1 paper); cancer (1); Hepatic fibrosis (1); memory impairment (1); myocardial infarction (1); steatosis (1).